IL9 (interleukin 9)
Diseases named in the same sentence as IL9 in open-access papers (continued):
Sharing a sentence is not in itself a finding about the gene and the disease.
fibrosis (8 papers, 2021 to 2024). the formation of excess fibrous connective tissue in an organ or tissue in a reparative or reactive process. "The protective role of VISTA in tubulointerstitial fibrosis via the IFN-γ/IL-9 axis after glomerular injury could be reflected in human glomerulonephritis, wherein VISTAhi kidneys had low fibrosis and better prognosis than VISTAlo kidneys." (PMID 34752423, 2022). "IL-9 and IL-10 levels were significantly higher in the PBMC supernatants stimulated with SEA in patients with fibrosis." (PMID 34970264, 2021). "Recently, interleukin-9 (IL-9) is increased in liver cirrhosis and CHB with fibrosis." (PMID 36359782, 2022). "In vivo, IL-9 was elevated during experimental chronic infection in BALB/c mice, and this cytokine played a protective role in the immunopathological response during this phase by controlling cardiac fibrosis and proinflammatory cytokine production." (PMID 34722343, 2021). "In our study, eight cytokines (CCL21, a T-cell chemoattractant, IL-9, IL-17F, IL-21, IL-28A, I-309, MIP-1β, and TARC) significantly correlated with BDG exposure in those without fibrosis, while only two cytokines (eotaxin-3 and M-CSF) were correlated in those with fibrosis." (PMID 39502781, 2024). "During CHC treatment, patients with SLD had distinct cytokine and growth factor kinetics, with SLD being the main source of variation in several cytokines (IL-5, IL-9, IL-10, IL-13, IL-17A, IL-22) and growth factors (EGF, VEGF and ANG), and it seems this was independent of fibrosis stage." (PMID 39200991, 2024).
Hodgkins lymphoma (8 papers, 2010 to 2022). A heterogeneous group of malignant lymphoid neoplasms of B-cell origin characterized histologically by the presence of Hodgkin and Reed-Sternberg (HRS) cells in the vast majority of cases. "Furthermore, IL-9 secreted by Hodgkin’s Reed Sternberg cells has been implicated in the recruitment of eosinophils in the classical Hodgkin Lymphoma microenvironment." (PMID 33146828, 2021). "This concept is in agreement with the finding that IL-9 promotes the development of many hematological human tumors, including Hodgkin’s lymphoma and B cell lymphoma suggesting the presence of pro-tumoral effects of IL-9 in several tumor entities." (PMID 35514957, 2022). "Other reports have shown that IL-9 can promote the progression of different hematological system tumors, such as Hodgkin’s lymphoma, acute lymphoblastic leukemia and NK T cell lymphoma." (PMID 32228589, 2020). "IL-9 was also expressed in two of six cases of large cell anaplastic lymphoma and in 6 of 13 cases of Hodgkin's disease by northern blot analysis or in situ hybridization." (PMID 24722378, 2014). "However, in hematological neoplasms such as chronic lymphocytic leukemia, Hodgkin’s lymphoma and diffuse large B lymphoma, IL-9 is generally considered to promote tumor progression via its lymphocyte growth factor function." (PMID 32228589, 2020). "Notably, IL-9 overexpression induces thymic lymphomas in mice, and IL-9 production has an effect on Hodgkin’s disease and human T-lymphotropic virus type I (HTLV-I)-transformed T cells in humans." (PMID 24520283, 2014). "Several studies have indicated that IL-9 may promote oncogenesis during Hodgkin's Lymphoma (HL) and large cell anaplastic lymphoma in addition to its significant regulatory role in allergy and autoimmunity." (PMID 24722378, 2014). "An increased expression level of IL-9 in the serum has been observed as a negative prognostic factor in patients with Hodgkin’s lymphoma and extranodal NK/T-cell lymphoma." (PMID 33803218, 2021). "IL-9 was also found to be expressed by Hodgkin- and Sternberg-Reed cells in cases of Hodgkin's lymphomas, which were employed as a positive control for IL-9 staining (not shown)." (PMID 21297223, 2010).
periodontitis (8 papers, 2020 to 2025). An acute or chronic inflammatory process that affects the tissues that surround and support the teeth. "We find that genetic proxies of circulating concentration of IL9 are positively associated with the risk of periodontitis, and those of IL17 are negatively with the risk of periodontitis." (PMID 36793899, 2023). "Using MR approach, we show that elevated circulating concentrations of IL9 predispose individuals to the development of periodontitis." (PMID 36793899, 2023). "Although IL9 has been understudied in the field of periodontitis, our study provides a genetic basis for a causal relationship between IL9 and periodontitis." (PMID 36793899, 2023). "When using SNPs obtained with the higher cut-off (p < 5 × 10−6), the MR study reveals that genetically predicted circulating IL9 is potentially associated with periodontitis (OR = 1.199, 95%CI: 1.049–1.372 p = 0.008) based on the IVW method." (PMID 36793899, 2023). "Diagnostic model of Grade C periodontitis was constructed combining IL-1β and IL-9 GCF levels and showed an accuracy of 0.92 with high sensitivity (0.94) and specificity (0.89)." (PMID 33218047, 2020). "Estimation of associations between circulating IL9, IL17 and risk of periodontitis using Mendelian randomization analysis." (PMID 36793899, 2023). "IL9 exhibits pro-inflammatory activities in a range of diseases, but its role in periodontitis is unclear." (PMID 36793899, 2023). "Future studies are warranted to understand the regulation of IL9 in periodontitis in more details, to identify relevant target cells of IL9, and to delineate the mechanisms that mediate the effects of IL9 in periodontitis." (PMID 36793899, 2023). "Despite the similar clinical improvement in response to non-surgical periodontal treatment, moderate pockets of grade C periodontitis patients still presented higher IL-1β and lower IL-9 GCF levels." (PMID 33218047, 2020). "In our study, IL9 and IL17 were found to be genetically associated with periodontitis." (PMID 36793899, 2023). "A previous meta-analysis assessing genetic polymorphisms of IL9 in Chinese non-smokers has suggested that IL9 does not have a causal relationship with periodontitis." (PMID 36793899, 2023). "Our study reveals a genetic link between IL9 and periodontitis." (PMID 36793899, 2023). "Furthermore, it was observed that IL-1β was higher in GCF compared to IL-9 levels in moderate periodontitis sites." (PMID 35270581, 2022). "A significant increase in IL-9 concentration was also observed at moderate pocket sites 3 months after the completion of non-surgical periodontal therapy in patients with aggressive periodontitis." (PMID 33218047, 2020). "A mathematical model was constructed to identify Grade C periodontitis patients based on the subjects’ GCF levels of IL-1β and IL-9, which achieved an area under the receiver-operating characteristic (ROC) curve of 0.94." (PMID 33218047, 2020). "Concerning the IL-9 levels of moderate and deep sites, no significant changes were detected after treatment within each periodontitis group." (PMID 33218047, 2020). "Therefore, the primary aim of this preliminary study was to investigate GCF levels of IL-1β, IL-9, TNF-α, and VEGF before and after non-surgical periodontal treatment in patients suffering from stage III periodontitis with moderate and rapid rates of progression." (PMID 33218047, 2020).
systemic sclerosis (8 papers, 2012 to 2025). A chronic disorder, possibly autoimmune, marked by excessive production of collagen which results in hardening and thickening of body tissues. "There are also some reports of increased IL-9 levels in relation to systemic sclerosis and experimental transplant allograft rejection." (PMID 24023645, 2013). "Furthermore, in systemic sclerosis, heightened IL-9 expression in diseased skin could promote B cells to produce autoantibodies." (PMID 38605942, 2024).
anaphylaxis (7 papers, 2012 to 2023). An acute hypersensitivity reaction that occurs from exposure to an allergen. "While IL-9-deficient mice fail to develop oral antigen-induced anaphylaxis, the overexpression of intestinal IL-9 induces an anaphylactic phenotype." (PMID 37296626, 2023). "Previously, IL-9 has been found to be associated with anaphylaxis induction." (PMID 38139075, 2023). "IL-9 increases susceptibility to passive or active systemic anaphylaxis." (PMID 22413008, 2012). "The extensive roles played by IL-9 in immune regulation and effector mechanisms in humans are beyond the scope of this report but we note murine studies indicating that IL-9 can promote systemic anaphylaxis." (PMID 23071516, 2012). "Based on fold-change analyses, we identified four immune markers (IL-6, IL-9, IL-17E, MIP-3a) that were of high importance (4–5.9-fold or higher) during anaphylaxis." (PMID 38139075, 2023). "Our findings provide support for the potential role of IL-9 in CMA pathogenesis, potentially through its influence on intestinal anaphylaxis." (PMID 35215473, 2022). "It remains to be elucidated if the resistance to IL-9-driven and mast cell-induced intestinal anaphylaxis in C57BL/6 mice reflected a different function of IL-9 and mast cells in the different mouse strains or different control of IL-9 production." (PMID 24516385, 2014). "However, IL-9 signaling plays an important role only in oral antigen-induced anaphylaxis, not in parenteral antigen-induced systemic anaphylaxis." (PMID 37296626, 2023).
chronic lymphocytic leukemia (7 papers, 2020 to 2025). "IL-9 has been recently implicated in the pathogenesis of chronic lymphocytic leukemia; however, the molecular mechanisms underlying its contribution to this complex neoplasia are still unclear." (PMID 34944921, 2021). "Recently, IL-9 has been implicated in the development of chronic lymphocytic leukemia, although the underlying molecular mechanism remains unknown." (PMID 34944921, 2021). "Here, we summarize the current knowledge of IL-9 in the tumor microenvironment, with a focus on its role in the pathogenesis of chronic lymphocytic leukemia." (PMID 34944921, 2021). "Here, we summarize the current knowledge concerning the roles of IL-9 in disease, with a focus on its implication in the pathogenesis of chronic lymphocytic leukemia." (PMID 34944921, 2021). "High expression of IL-9 was detected in chronic lymphocytic leukemia (CLL), adult T-cell leukemia (ACTL), Hodgkin lymphoma (HD), anaplastic large-cell lymphoma (ALCL) and NKT cell lymphoma by different groups." (PMID 32508847, 2020). "Studies examined biopsies and serum samples from patients with B-cell chronic lymphocytic leukemia (CLL) and found that the levels of IL-9 mRNA and protein expression were altered and correlated with Rai staging, ZAP70, and CD38." (PMID 37048814, 2023). "In addition, IL-9 was significantly increased in the PBMC of chronic lymphocytic leukemia (CLL) patients compared with levels in normal individuals, and the increased IL-9 was related to the clinical staging, ZAP-70 expression, β2 microglobulin expression and IgVH status of CLL patients." (PMID 32228589, 2020). "While in hematologic tumors, including chronic lymphocytic leukemia (CLL), Hodgkin lymphoma (HL), and DLBCL, it is generally acknowledged that IL-9 promotes tumor progression through the T-lymphocyte growth factor." (PMID 35211408, 2022).
Hypertension (7 papers, 2020 to 2024). The presence of chronic increased pressure in the systemic arterial system. "Hypertension progression was associated with VEGF-A, IL-6, IL-4, and MCP-3, while newly detected hypertension was linked to IL-9, TNFa, IL12(p40), IFNa2, and EGF." (PMID 37629267, 2023). "In the present study, IL-9 KO mice were used to investigate the effects of IL-9 on Ang II-induced hypertension and to explore possible underlying mechanisms." (PMID 32148441, 2020). "In addition, multivariate analysis was performed to investigate the risk factors of hypertension that influence IL-9 secretion." (PMID 32148441, 2020). "The positive correlations of Mycosphaerella with both TNFβ and IL9 in HTN+CKD patients suggest a potential immunoregulatory role for this fungal genus in the complex interplay between hypertension and chronic kidney disease." (PMID 38162661, 2023). "Then, we further investigated the role of IL-9 KO on hypertension and IL-9 KO reduced blood pressure." (PMID 32148441, 2020). "In the present study, we found for the first time that IL-9 levels were significantly increased in both patients with hypertension and the Ang II-induced mouse model of hypertension." (PMID 32148441, 2020). "Serum IL-9 levels were higher in patients with hypertension than in control subjects." (PMID 32148441, 2020). "We aimed to investigate whether IL-9 affects angiotensin II- (Ang II-) induced hypertension in mice." (PMID 32148441, 2020). "Our data showed that IL-9 can significantly regulate Ang II-induced hypertension, which might be mediated by the STAT3 pathway." (PMID 32148441, 2020). "To investigate whether IL-9 is involved in hypertension through the regulation of inflammatory response, we detected STAT3 phosphorylation." (PMID 32148441, 2020). "Thus, IL-9 might be a novel therapeutic agent for the prevention and treatment of clinical hypertension." (PMID 32148441, 2020). "IL-9 might be a novel target for the treatment and prevention of clinical hypertension." (PMID 32148441, 2020). "Furthermore, circulating IL-9 levels in patients with hypertension were measured." (PMID 32148441, 2020). "The results may suggest that IL-9 may participate in the process of Ang II-induced hypertension." (PMID 32148441, 2020). "Additionally, IL-9 KO plays a protective role in the Ang II-induced hypertension model." (PMID 32148441, 2020). "However, whether IL-9 affects Ang II-induced hypertension is still unknown." (PMID 32148441, 2020). "IL-9 is a characteristic inflammatory cytokine, and the role of IL-9 in hypertension has not been reported." (PMID 32148441, 2020).
type 2 diabetes (7 papers, 2012 to 2025). "We found decreased IL-9 levels in human type 2 diabetes patients and decreased IL-9 signaling in high-fat diet (HFD)-induced obese mice." (PMID 40962954, 2025). "Specifically, patients with type 2 diabetes showed a significant decrease in IL-9 (U = 389, P < 0.001) and CCL4 (U = 774.5, P < 0.001) concentrations compared to control participants." (PMID 41030257, 2025). "Vasanthakumar and coworkers reported that serum levels of IL-9 were lower in adults with type 2 diabetes and normal kidney function compared to healthy subjects." (PMID 35445345, 2022). "Although NLRP3 is a well-known instigator of type 2 diabetes, the possibility that the IL-9 pathway could exert its protective effects by regulating the NLRP3 inflammasome has not been investigated thus far." (PMID 40962954, 2025). "Finally, we investigated the role of IL-9 in helminth-mediated protection during type 2 diabetes." (PMID 40962954, 2025). "To date, there are no reports showing a possible interaction between the IL-9 pathway and the inflammasome in type 2 diabetes." (PMID 40962954, 2025).
airway hyperresponsiveness (6 papers, 2005 to 2024). "The quantity of Th9 cells correlates directly with the severity of airway hyperresponsiveness and airway inflammation, which can be alleviated by anti-IL-9 treatment." (PMID 27518187, 2016). "Activated IL-13 and IL-9 can promote allergen-induced airway hyperresponsiveness." (PMID 35744915, 2022).
B cell lymphoma (6 papers, 2016 to 2024). "Previous studies have demonstrated that the serum IL-9 level is elevated in patients with B-cell NHL (including some patients with DLBCL)." (PMID 35211408, 2022). "IL-9 has also been demonstrated to enhance the Treg and mastocyte-mediated immunosuppression effects to participate in the pathogeneses of B-cell NHL." (PMID 35211408, 2022). "They found that the number of Treg cells and mast cells as well as the expression of IL-9, were increased in B-cell NHL patients." (PMID 32508847, 2020). "Our previous study demonstrated that there was an elevated serological level of IL-9 in some B-cell NHL patients (including several DLBCL cases)." (PMID 27364124, 2016). "Neutralizing IL-9 with certain specific antibodies inhibited tumor growth in murine models of B-cell lymphoma." (PMID 27364124, 2016). "In our previous study, IL-9 was demonstrated to take part in the pathogenesis of B-cell NHL by augmenting the extent of immunosuppression that is mediated by Treg cells and mast cells." (PMID 27364124, 2016). "IL-9 has been shown to promote the development of multiple human liquid tumors, including nasal natural killer (NK)/T-cell lymphoma, anaplastic large-cell lymphoma, and B-cell non-Hodgkin’s lymphoma, and the IL-9 antibody can inhibit the proliferation of these cells." (PMID 38473379, 2024).
bronchiolitis (6 papers, 2007 to 2023). Inflammation of the bronchioles characterized by swelling of the bronchioles and mucus accumulation. "In humans, for example the IL9 genetic polymorphism (rs2069885) has an opposite effect on the risk of severe respiratory syncytial virus bronchiolitis in boys and girls." (PMID 21666791, 2011). "Mcnamava and Scruple reported that IL-9 increased in the peripheral serum of children with bronchiolitis, suggesting that IL-9 is involved in the airway inflammatory response of bronchiolitis, which is consistent with our study." (PMID 33514798, 2021). "In this study, there was significant difference for IL-9 between the bronchiolitis group and the normal control group (P < 0.05)." (PMID 33514798, 2021). "The data obtained showed that IL-9 levels in BALF were increased in infants with severe bronchiolitis that required oxygenation." (PMID 30936869, 2019). "In another study performed in pre-term and term infants with hRSV bronchiolitis, the expression of the IL-9 mRNA in BALF was increased in both groups, as compared to control groups." (PMID 30936869, 2019). "Following reports that bronchial secretions from infants with respiratory syncitial virus (RSV) bronchiolitis contained high levels of IL-9, the function of IL-9 was specifically investigated in a murine model of RSV vaccination and infection." (PMID 24586147, 2014). "Remarkably, it has been reported that IL-9 can upregulate genes involved in the mucus production in goblet cells, which could explain the elevated amounts of mucus in patients with hRSV-induced bronchiolitis." (PMID 30936869, 2019). "The bronchiolitis group serum IL-5, IL-9, IL-13, IL-33, TSLP protein levels were higher than the normal control group." (PMID 33514798, 2021).
Crohn disease (6 papers, 2010 to 2025). A gastrointestinal disorder characterized by chronic inflammation involving all layers of the intestinal wall, noncaseating granulomas affecting the intestinal wall and regional lymph nodes, and transmural fibrosis. "For example, the increased serum IL-9 level is associated with the disease activity of UC and Crohn’s disease." (PMID 38605942, 2024). "We confirm previously reported disease related pathways and provide evidence for IL-2 Receptor Beta Chain in T cell Activation and IL-9 signaling as Crohn's disease associated pathways." (PMID 20584322, 2010). "Approximately 41% of individuals with IBD had detectable levels of serum IL-9, and the level of IL-9 in the serum of individuals with Crohn’s disease correlated with disease severity and poor prognosis." (PMID 33374787, 2020). "Furthermore, a number of clinical studies have revealed that serum levels of IL-9 in patients with UC or Crohn's disease (CD) are higher than those in controls, and increased levels of IL-9 are significantly associated with inflammatory activity in the bowel in patients with UC or CD." (PMID 31637216, 2019). "Elevated percentages of PU.1+, IL-9R+, CD3+IL-9+, CD4+IL-9+, and IRF4+IL-9+ T cells were observed in the lamina propria and epithelium of patients with UC and Crohn’s disease (CD) compared to those in healthy controls." (PMID 40771819, 2025).